PNPLA6 (patatin like domain 6, lysophospholipase )
Description:
Phospholipase B that deacylates intracellular phosphatidylcholine (PtdCho), generating glycerophosphocholine (GroPtdCho). This deacylation occurs at both sn-2 and sn-1 positions of PtdCho. Catalyzes the hydrolysis of several naturally occurring membrane-associated lipids. Hydrolyzes lysophospholipids and monoacylglycerols, preferring the 1-acyl to the 2-acyl isomer. Does not catalyze hydrolysis of di- or triacylglycerols or fatty acid amides.
Synonyms: NTE; sws; iPLA2delta; SPG39; BNHS; LNMS; NTEMND; OMCS
Tractability: Antibody: UniProt predicts a signal peptide or a membrane-spanning region. PROTAC: ubiquitination databases record sites on it; its protein half-life has been measured.
Target class: Enzyme
Gene: Protein-coding gene on chromosome 19 (7,534,004 to 7,561,764, forward strand). Ensembl gene ENSG00000032444.
Subcellular location: Endoplasmic reticulum membrane
Subcellular location (Human Protein Atlas): Cytosol; Endoplasmic reticulum
Pathways (Reactome):
Metabolism: Glycerophospholipid catabolism
Gene Ontology:
Molecular function: phosphatidylcholine lysophospholipase activity; phospholipase B activity; monoacylglycerol lipase activity
Biological process: glycerophospholipid catabolic process; lipid metabolic process; phosphatidylcholine metabolic process
Cellular component: endoplasmic reticulum membrane; membrane; endoplasmic reticulum
Genetic constraint (gnomAD): Loss-of-function variants: 99 observed, 134.14 expected, observed/expected ratio (o/e) 0.74, 90% interval 0.63 to 0.87. The upper end of that interval is the gene's LOEUF score, 0.87, which puts it in group 3 of 6, group 1 being the genes least tolerant of losing a copy. Missense variants: 1,409 observed, 1,821.2 expected, observed/expected ratio (o/e) 0.77, 90% interval 0.74 to 0.81. Synonymous variants: 815 observed, 786.78 expected, observed/expected ratio (o/e) 1.04, 90% interval 0.98 to 1.1.
Gene-disease validity (ClinGen):
ClinGen rates the evidence that PNPLA6 causes each of these diseases.
PNPLA6-related spastic paraplegia with or without ataxia (autosomal recessive): Definitive. An autosomal recessive, multisystem condition caused by pathogenic variants of the PNPLA6 gene that characterized by peripheral neuropathy, cognitive impairment, lower limb spasticity, muscle weakness, and reduced vibration sense.
Homologues: Orthologues: chimpanzee PNPLA6 (99% identical), macaque PNPLA6 (96% identical), rat Pnpla6 (95% identical), pig PNPLA6 (95% identical), dog PNPLA6 (94% identical), mouse Pnpla6 (93% identical), rabbit PNPLA6 (92% identical), guinea pig PNPLA6 (92% identical), zebrafish pnpla6 (72% identical), Drosophila melanogaster sws (41% identical), Caenorhabditis elegans ZK370.4 (35% identical). Paralogues in human: PNPLA7 (59% identical).